LILRB1 (leukocyte immunoglobulin like receptor B1)
Diseases named in the same sentence as LILRB1 in open-access papers (continued):
Sharing a sentence is not in itself a finding about the gene and the disease.
liver cancer (2 papers, 2022 to 2025). An epithelial or non-epithelial malignant neoplasm that arises from the liver. "Our study revealed that the mRNA expression of LILRB1, LILRB2, LILRB3, and LILRB5 was downregulated, while compared with normal tissues, the mRNA expression of LILRB4 was upregulated in liver cancer tissues." (PMID 35321724, 2022).
Miscarriage (2 papers, 2016 to 2017). A pregnancy that ends at a stage in which the fetus is incapable of surviving on its own, defined as the spontaneous loss of a fetus before the 22th week of pregnancy. "Moreover, a study performed by our group on the KIR, LILRB1 and HLA-G association with spontaneous miscarriage indicated that polymorphism of partners in KIR2DL4 could be associated with susceptibility to miscarriage of their women." (PMID 28523429, 2017). "Multivariate analysis indicated that women’s −716 HLA-G and LILRB1 and men’s KIR2DL4 9A/10A are important in terms of the protection or susceptibility to miscarriage, respectively (p = 0.00968)." (PMID 26973020, 2016).
parasitemia (2 papers, 2022 to 2023). "When NK cells were treated with anti-LILRB1 neutralizing antibody, the parasitemia reduction difference between 3D7 and 3D7 AS was abrogated (63.9 ± 4.7% vs 54.5% ± 3.8)." (PMID 35831417, 2022).
relapsing-remitting MS (2 papers, 2021 to 2025). "Those with progressive multiple sclerosis are reported to have a larger number of circulating LILRB1+ CD8+ T lymphocytes and LILRB1+ natural killer cells in comparison to patients with relapsing-remitting multiple sclerosis." (PMID 40255388, 2025).
abortion (1 paper, 2016). the ending of pregnancy by removing a fetus or embryo before it can survive outside the uterus. "In our case–control study, we tried to elucidate an association of particular genetic variants of KIR2DL4, LILRB1 and its ligand HLA-G in women as well as in their partners with susceptibility to spontaneous abortion." (PMID 26973020, 2016). "We found a protective effect of women’s heterozygosity in −716 HLA-G (p = 0.0206) and LILRB1 (p = 0.0131) against spontaneous abortion." (PMID 26973020, 2016).
acute lymphoblastic leukemia (1 paper, 2025). Leukemia with an acute onset, characterized by the presence of lymphoblasts in the bone marrow and the peripheral blood. "Herein, we identified leukocyte-immunoglobulin-like-receptor-B1 (LILRB1, CD85j) as a novel target for CAR-T cells through cell surface proteomics on patient-derived samples of high-risk B-cell acute lymphoblastic leukemia (B-ALL)." (PMID 40186066, 2025).
diffuse large B-cell lymphoma (1 paper, 2024). "A notable trend of increased expression of LILRB1 BM macrophages has been observed in diffuse large B-cell lymphoma (DLBCL) patients who had BM infiltrating disease compared with those who do not." (PMID 39696628, 2024).
kidney transplant (1 paper, 2025). A surgical procedure in which one or both kidneys from a donor are implanted into a recipient. "Recent findings underscore the immunological relevance of LILRB1 in the context of kidney transplant rejection." (PMID 41562090, 2025).
latent infection (1 paper, 2023). "Our data further suggest that the inhibitor receptor LILRB1 potentially restricts the clonal expansion of high-avidity CMV-specific T cell clonotypes during latent infection." (PMID 38053994, 2023). "Among them, we identified LILRB1 encoding for an inhibitory receptor (also known as CD85j or ILT2/LIR-1), associated in CD8 T cells with aging and CMV latent infection." (PMID 38053994, 2023).
ovarian carcinoma (1 paper, 2023). A malignant neoplasm originating from the surface ovarian epithelium. "Moreover, in ovarian cancer a high content of LILRB1-positive immune cells was correlated with shorter survival, and worse adjuvant chemotherapy responses." (PMID 37781391, 2023).
rheumatoid arthritis (1 paper, 2015). A chronic, systemic autoimmune disorder characterized by inflammation in the synovial membranes and articular surfaces. "Therefore, we could suggest that in rheumatoid arthritis patients, high levels of sHLA-G molecules with capability to bind to LILRB1 could also impair the production of auto-antibodies." (PMID 25853899, 2015).
sarcoma (1 paper, 2023). A usually aggressive malignant neoplasm of the soft tissue or bone. "This study is the first to investigate soluble forms of the macrophage markers SIRPα, LILRB1, CD163, and CD206 in sarcoma, and its conclusions are in accordance with a large study conducted by Dancsok showing that SIRPα in tissue samples is an adverse prognostic factor for soft tissue sarcomas." (PMID 36900335, 2023).
tuberculosis (1 paper, 2024). A chronic, recurrent infection caused by the bacterium Mycobacterium tuberculosis. "The immune inhibitory receptor leukocyte immunoglobulin like receptor B1 (LILRB1), which is upregulated and activated by human leukocyte antigen-G (HLA-G), drives natural killer (NK) cell exhaustion in tuberculosis (TB) patients, thus serving as a promising target for TB immunotherapy." (PMID 39030302, 2024).
vasculitis (1 paper, 2024). "Additionally, genes such as LILRB1 and Fc alpha receptor (CD89) have also been reported to play a role in immune response as vasculitis." (PMID 38361743, 2024).
vitiligo (1 paper, 2023). Generalized well circumscribed patches of leukoderma that are generally distributed over symmetric body locations and is due to autoimmune destruction of melanocytes. "Moreover, a consistent second-order combination involving HLA-G (rs9380142) and LILRB1 (rs2114511) was identified, indicating an epistatic interaction role between HLA-G and LILRB1 alleles in vitiligo pathogenesis." (PMID 36831297, 2023). "The most significant model associated with vitiligo using MDR v.3.0.2 was a second-order combination between HLA-G rs9380142 and LILRB1 rs2114511, accurately classifying 65% of tested individuals in 9 out of 10 validation intervals." (PMID 36831297, 2023). "Despite the latest advances in vitiligo, the role of the simultaneous genetic composition of HLA-G, LILRB1, and LILRB2 in disease development remains to be elucidated." (PMID 36831297, 2023). "Here we investigated the LILRB1 and LILRB2 association with vitiligo risk and evaluated the possible role of interactions between HLA-G and its receptors in this pathogenesis." (PMID 36831297, 2023). "We tested the association of the polymorphisms of HLA-G, LILRB1, and LILRB2 with vitiligo using logistic regression along with adjustment by ancestry." (PMID 36831297, 2023). "Accordingly, whether or not individual polymorphisms in HLA-G, LILRB1, and LILRB2 were associated with susceptibility to vitiligo and whether or not there were some epistatic interactions between them were, therefore, investigated here." (PMID 36831297, 2023). "However, no study has evaluated the role of LILRB1 and LILRB2 polymorphisms in developing vitiligo or the possible interactions between HLA-G and the genes encoding its receptors." (PMID 36831297, 2023).
tumor (148 papers, 2009 to 2026). "HNSCC patients with high LILRB1 expression exhibited a better prognosis, which was influenced by tumor mutation burden." (PMID 41879001, 2026). "Within the TME, LILRB1 was predominantly localized to M2-type TAMs, with high expression predicting advanced tumor stage, increased recurrence risk, and unfavorable prognosis." (PMID 40860159, 2025). "In the GC microenvironment, LILRB1‐positive tumor‐associated macrophages (TAMs) typically exhibit an M2‐like phenotype." (PMID 40686307, 2025). "For example, a clear association of LILRB1 expression level with advanced tumor stages and inferior survival rate has been demonstrated in gastric cancer." (PMID 38911856, 2024). "Concurrently, the degradation of tumor-derived LILRB1 would render tumor cells more susceptible to ferroptosis and effectively impede tumor progression." (PMID 38982045, 2024). "In Tumor microenvironment (TME), the expression of LILRB1 is mainly restricted in tumor stroma with tumor-associated macrophages as the major immune cell populations." (PMID 38911856, 2024). "For instance, binding between HLA class I on cancer cells and leukocyte immunoglobulin-like receptor 1 (LILRB1) expressed on monocytes, dendritic cells, and tumor-associated macrophages transduces an inhibitory signal that blocks phagocytosis." (PMID 37958404, 2023). "The LILRB1 expression was significantly associated with large tumor size (>5 cm), deep tumor invasion, and lymph node metastasis." (PMID 34485116, 2021). "Immunohistochemistry and bioinformatic analysis showed that LILRB1 had a significant positive correlation with M2 tumor-associated macrophages (TAMs) infiltration." (PMID 34485116, 2021). "High-LILRB1 expression was associated with more advanced tumor stage, higher recurrence risk and worse survival." (PMID 34485116, 2021). "Increased LILRB1 expression was linked with more advanced tumor grades (P < 0.001)." (PMID 37142967, 2023). "Anchored by glycosyl phosphatidylinositol, CD24 interacts with sialic acid, binding immunoglobulin-like agglutinin-10 (SIGlec-10) to β2 M, which is overexpressed in some tumor tissues and binds to LILRB1 on macrophages to inhibit phagocytosis, resulting in a loss of immune surveillance." (PMID 35892835, 2022). "The fact that certain tumor cells highly express β2M, which could bind to LILRB1 on macrophages to inhibit phagocytosis, leading to the loss of immune surveillance, suggests that β2M is another self-label expressed by tumor cells." (PMID 34625124, 2021). "In addition, 5724G>A in LILRB1 gene was associated with protection from tumor cell infiltration of regional lymph nodes." (PMID 27652273, 2016). "Critically, tumor cells induced LILRB1 expression in NK cells while downregulating activating receptors, including NKp46, NKG2D, and CD16, thereby impairing tumor recognition." (PMID 40860159, 2025). "To explore the utility of LILRB1 for the elimination of tumor cells, we further analyzed its mRNA expression in various pediatric B-cell malignancies from the St." (PMID 40186066, 2025). "Engineered exosomes expressing SIRPα, PD-1, and LILRB1 interact with receptors on tumor cells (CD47, PD-L1, and B2M), promoting the phagocytosis of tumor cells and enhancing antigen presentation by immune cells." (PMID 39465690, 2025). "Blocking LILRB1 signaling in combination with checkpoint blockade enhances cytotoxic T cell infiltration, remodels the tumor immune landscape, and delays tumor growth in preclinical models." (PMID 40821795, 2025). "Decreased cholesterol levels in the MM cells from LILRB1 KD mice were consistent with decreased tumour burden, while overexpression resulted in significantly greater tumour burden." (PMID 40853521, 2025). "Mice treated with two doses of either LILRB1 CAR-T cells or CD19 CAR-T cells exhibited a significant reduction in tumor burden, as measured by bioluminescent imaging, and had markedly prolonged survival compared to those receiving MOCK T cells." (PMID 40186066, 2025).
tumor (continued). "In colorectal cancer (CRC), dual inhibition of LILRB1 and PD-L1 leads to enhanced dendritic cell activation, improved cross-presentation of tumor antigens, and greater expansion of tumor-specific CD8+ T cells, outperforming either monotherapy alone." (PMID 40821795, 2025). "To assess potential off-tumor toxicity across normal leukocytes, we conducted co-culture experiments with LILRB1 CAR-T cells and healthy donor peripheral blood mononuclear cells (PBMC)." (PMID 40186066, 2025). "Increased expression of LILRB1 is known to play a role in immune suppression, but its role in tumour biology has yet to be fully defined." (PMID 40853521, 2025). "Blocking antibodies targeting LILRB1-mediated signaling have previously been shown to enhance NK cell antitumor activity and tumor cell killing." (PMID 40186066, 2025). "For example, in chronic lymphocytic leukimia, combination of LILRB1 antibody with lenalidomide promotes lysis of tumor cells through activation of NK cells." (PMID 38911856, 2024). "As a result, activation of LILRB1 can impact the clearance of pathogens and/or tumor cells through inhibition of innate immune system." (PMID 38911856, 2024). "We found that CTR-KD MM cells had fewer lipid ROS than LILRB1-KD MM cells, and the percentage and number of CTR-KD MM cells in the BM of tumor-bearing mice were significantly higher than those bearing LILRB1-KD MM cells." (PMID 38982045, 2024). "Overall, these results demonstrate that, by facilitating LDL/cholesterol uptake, LILRB1 plays an important role in maintaining cholesterol metabolic homeostasis to protect MM cells from induction of ferroptosis in tumor microenvironment." (PMID 38982045, 2024). "NSG mice bearing LILRB1-KD MM cells displayed significantly slower tumor growth, lower tumor burden, impaired tumor infiltration into BM, and better survival compared to CTR-KD MM-bearing mice." (PMID 38982045, 2024). "Interaction between HLA-G on tumor cells and LILRB1-expressing NK cells and CD8+ T cells inhibits cytotoxicity through the ITIM/SHP-2-mediated pathway." (PMID 38785789, 2024). "Normally, LILRB1 signaling in macrophages prevents them from engulfing tumor cells, allowing the tumor to evade immune surveillance." (PMID 38911856, 2024). "MHC class I component β2-microglobulin which is expressed on the surface of tumor cells, and its receptor, leukocyte immunoglobulin like receptor subfamily B member 1 (LILRB1), expressed on membrane of macrophages provides another therapeutic target." (PMID 39003350, 2024). "Innate immune checkpoints, such as the CD47/SIRPα axis, PD-1/PD-L1 axis, and MHC-I/LILRB1 axis, play important roles in tumor-mediated immune escape from the clearance by phagocytosis." (PMID 38383737, 2024). "Together, this compelling evidence suggests that LILRB1 blockade can induce macrophage-mediated tumor elimination through enhancing antibody-dependent cellular phagocytosis." (PMID 38911856, 2024). "B1–176 is a humanized, Fc-engineered antibody to disrupt LILRB1 signaling and shows enhanced natural cytotoxicity against various tumor cell lines and in vivo xenografts." (PMID 38911856, 2024). "The intricate relationship between LILRB1 expression and the tumor microenvironment highlights its potential as a significant prognostic marker across different cancers, providing valuable insights into disease progression and treatment outcomes." (PMID 38911856, 2024). "MHC-I on tumor cells binds to LILRB1 and LILRB2, which are members of the LILR family, which belongs to the inhibitory class of the LIR receptor subfamily." (PMID 36882399, 2023). "As an inhibitor of B-cell growth, HLA-G probably exerts an inhibitory effect on tumor growth by interacting with LILRB1, suggesting that HLA-G-LILRB1 axis can be applied to the treatment of B-cell malignancies." (PMID 36882399, 2023).
tumor (continued). "LILRB1 has been reported to exert an immunoregulatory effect via interacting with a wide spectrum of HLA class I molecules, thus meditating tumor cell eradication and optimistic prognosis." (PMID 36864399, 2023). "A total of five potentially targetable tumor antigens were identified (PTPRC, SIGLEC10, CARD11, LILRB1, ADAMDEC1); high antigen expression was associated with prolonged OS and DFS, as well as higher tumor infiltration by antigen-presenting cells." (PMID 36992220, 2023). "In certain tumors, the fraction of LILRB1 expressing NK cells was increased in the tumor microenvironment." (PMID 37781391, 2023). "The analysis of cells in the tumor microenvironment of different types of solid tumors confirmed that LILRB1 was mainly expressed in the tumor stroma with TAM representing the major LILRB1 expressing immune cell population." (PMID 37781391, 2023). "Promising results were obtained with combinations of LILRB1-directed antibodies and tumor targeting antibodies, bispecific CD3 antibodies or other immune checkpoint inhibitors blocking CD47 or PD-1." (PMID 37781391, 2023). "Intriguingly, HLA class I molecules not only inhibit NK cell-mediated lysis of tumor cells but also function as ‘Don`t Eat Me!’ signals that prevent malignant cells from phagocytic uptake by macrophages through LILRB1 engagement." (PMID 37781391, 2023). "Regarding the suggested interplay between the two axes CD47:SIRPα and HLA class I:LILRB1 in counteracting effective ADCP of tumor cells as demonstrated for anti-EpCAM or anti-EGFR antibodies, additional antibody combinations were studied." (PMID 37781391, 2023). "In contrast, LILRB1 was more rarely expressed in tumor infiltrating T cells and rather restricted to CD8-positive T cells with a TEMRA phenotype." (PMID 37781391, 2023). "In the tumor microenvironment, LILRB1 is expressed by different immune cells and was suggested to support tumor growth indirectly by contributing to the repression of multiple anti-tumoral functions." (PMID 37781391, 2023). "Nevertheless, a recent study has demonstrated that the common MHC class I component β2-microglobulin can bind to the inhibitory receptor LILRB1 of macrophages, thereby protecting tumor cells from phagocytosis and promoting resistance to immunotherapy." (PMID 36091041, 2022). "Because cell lines do not reflect the clinical heterogeneity of patients, the dual checkpoint blockade of CD47 and LILRB1 was investigated using tumor cells from patients." (PMID 36389667, 2022). "In this study, LILRB1 was shown to be more prevalent than LILRB2 in both healthy donor-derived macrophages and tumor-associated macrophages." (PMID 35865547, 2022). "These tumor cells induce the expression of inhibitory receptors (ILT2/LILRB1) and downregulate the expression of NK-cell-activating receptors NKp46, NKG2D and CD16, thereby preventing recognition and killing via NK cells." (PMID 35892678, 2022). "As such, LILRB1 blockade (clone VMP55) augments tumor cell phagocytosis by macrophages, supporting the potential of modulating the HLA class I/LILRB1 signaling axis to promote antitumor immunity." (PMID 35076022, 2022). "Researchers have also found that disruption of either MHC class I or LILRB1 enhanced phagocytosis of tumor cells in macrophages." (PMID 35321724, 2022). "Major Histocompatibility Complex (MHC) Class I expressed on the surface of tumor cells engages with Leukocyte Immunoglobulin Like Receptor B1 (LILRB1) on the surface of M2 TAMs to inhibit macrophage phagocytosis of the tumor cells." (PMID 34830776, 2021). "Next, we found an interesting phenomenon that LILRB1 had a significant positive correlation with M2 TAMs infiltration, considered immunosuppressive cells that promote tumor progression." (PMID 34485116, 2021). "As a major immunosuppressive receptor, LILRB1 plays a critical role in the escaping of tumor cells from immune surveillance." (PMID 34485116, 2021).